OAZ2 (ornithine decarboxylase antizyme 2)
Description:
Ornithine decarboxylase (ODC) antizyme protein that negatively regulates ODC activity and intracellular polyamine biosynthesis and uptake in response to increased intracellular polyamine levels. Binds to ODC monomers, inhibiting the assembly of the functional ODC homodimers. Does not target the ODC monomers for degradation, which allows a protein synthesis-independent restoration of ODC activity. Involved in the translocation of AZIN2 from ER-Golgi intermediate compartment (ERGIC) to the cytosol (By similarity).
Synonyms: AZ2
Tractability: No criterion of Open Targets' tractability assessment is met for any kind of drug.
Gene: Protein-coding gene on chromosome 15 (64,687,573 to 64,703,281, reverse strand). Ensembl gene ENSG00000180304.
Subcellular location: Nucleus
Subcellular location (Human Protein Atlas): Golgi apparatus
Pathways (Reactome):
Metabolism: Metabolism of polyamines; Regulation of ornithine decarboxylase (ODC)
Gene Ontology:
Molecular function: ornithine decarboxylase inhibitor activity; protein binding
Biological process: polyamine biosynthetic process; polyamine metabolic process; positive regulation of intracellular protein transport; positive regulation of protein catabolic process; biogenic amine metabolic process; negative regulation of polyamine transmembrane transport
Cellular component: cytoplasm; cytosol; nucleus
Genetic constraint (gnomAD): Loss-of-function variants: 13 observed, 17.81 expected, observed/expected ratio (o/e) 0.73, 90% interval 0.47 to 1.16. The upper end of that interval is the gene's LOEUF score, 1.16, which puts it in group 5 of 6, group 1 being the genes least tolerant of losing a copy. Missense variants: 206 observed, 214.18 expected, observed/expected ratio (o/e) 0.96, 90% interval 0.86 to 1.08. Synonymous variants: 94 observed, 81.67 expected, observed/expected ratio (o/e) 1.15, 90% interval 0.97 to 1.37.
Homologues: Orthologues: chimpanzee OAZ2 (100% identical), dog OAZ2 (100% identical), mouse Oaz2 (99% identical), guinea pig OAZ2 (98% identical), rabbit OAZ2 (97% identical), macaque OAZ2 (84% identical), pig OAZ2 (84% identical), rat Oaz2 (84% identical), tropical clawed frog oaz2 (81% identical), zebrafish oaz2a (53% identical), zebrafish oaz2b (44% identical). Paralogues in human: OAZ1 (51% identical), OAZ3 (31% identical).
Diseases named in the same sentence as OAZ2 in open-access papers:
OAZ2 is named in the same sentence as 12 diseases in open-access papers, as found by Europe PMC text mining. Sharing a sentence is not in itself a finding about the gene and the disease. The quoted sentences say what the papers report.
Colon Cancer (2 papers, 2018 to 2024). "Indeed, for example in colon cancer, it has been demonstrated that the OAZ2 mRNA stability is negatively regulated by miR-34a that directly targets OAZ2 3′UTR." (PMID 38918813, 2024). "Consequently, by revealing how OAZ2 is regulated by miR-34a at the posttranscriptional level, our findings suggest that miR-34a mimic and OAZ2 agonist may be repositioned to suppress cancer progression, dampen tumor evolution, and decrease the probability of adverse outcomes by MDR in colon cancer." (PMID 30175154, 2018).
gastric cancer (2 papers, 2018 to 2025). A primary or metastatic malignant neoplasm involving the stomach. "Indeed, a dramatic decrease in the expression of OAZ2 has been reported in gastric cancer and neuroblastoma, and high levels of OAZ2 expression are positively correlated with increased survival rate and favorable clinical prognosis." (PMID 30175154, 2018).
colon adenocarcinoma (1 paper, 2025). "Our study confirms OAZ2 as a significant prognostic indicator in colon adenocarcinoma (COAD), with a strong association to immune-related processes." (PMID 40032914, 2025). "Our study aims to dissect the specific role and mechanism of OAZ2 in colon adenocarcinoma, leveraging the capabilities of high-throughput sequencing technology and robust public databases like The Cancer Genome Atlas (TCGA)." (PMID 40032914, 2025). "Despite few studies focusing on the OAZ2 gene in colorectal cancer, its potential role in colon adenocarcinoma (COAD) prognosis and immune modulation remains underexplored." (PMID 40032914, 2025). "Our study is pioneering in reporting a correlation between low OAZ2 expression and poor prognosis in colon adenocarcinoma (COAD) patients." (PMID 40032914, 2025).
colorectal cancer (1 paper, 2025). A primary or metastatic malignant neoplasm that affects the colon or rectum. "Further investigations are needed to explore how these age-associated factors might interact with OAZ2 expression and influence prognosis in colorectal cancer." (PMID 40032914, 2025). "Despite these findings, research on the prognostic roles of OAZ2 in colorectal cancer (CRC) remains scarce." (PMID 40032914, 2025). "Overexpression of OAZ2 in RKO colorectal cancer cells significantly reduced their proliferation rate and impaired migration, confirming the functional impact of OAZ2 dysregulation in COAD." (PMID 40032914, 2025). "Experimental investigations into the biological role of OAZ2 in colorectal cancer cell dynamics revealed that overexpression of OAZ2 in RKO cells significantly reduces their proliferation and impairs migration, as shown by CCK-8 proliferation assays and scratch tests." (PMID 40032914, 2025). "To further investigate the effects of OAZ2 on colorectal cancer cell behavior, we transfected RKO cells with an OAZ2 overexpression plasmid." (PMID 40032914, 2025). "Our results further demonstrate that OAZ2 mRNA and protein levels are significantly reduced in COAD tissues compared to adjacent normal tissues, underscoring its potential tumor suppressive role in colorectal cancer." (PMID 40032914, 2025).
cancer (6 papers, 2018 to 2025). A tumor composed of atypical neoplastic, often pleomorphic cells that invade other tissues. "This differential expression was corroborated at the protein level, where Western blot analysis of tissues randomly selected from the cohort also showed reduced OAZ2 protein expression in cancer tissues compared to adjacent normal tissues." (PMID 40032914, 2025). "Despite its established significance in other cancers, the role of OAZ2 in COAD has been less explored." (PMID 40032914, 2025). "As a result, functional regulation of miR-34a/OAZ2 signaling was essential for the successful treatment of cancer with chemotherapy." (PMID 38725047, 2024). "The functional regulation of miR-34a/OAZ2 signaling was essential for the successful treatment of cancer using chemotherapy." (PMID 38725047, 2024). "As an endogenous ODC-activity antagonist, the antizyme 2 (OAZ2) expression is expected to be downregulated during cancer progression." (PMID 30175154, 2018). "Editing endows cancer stemness, up-regulates IL-8 to promote angiogenesis; delays c-Myc degradation via OAZ2-mediated non-ubiquitin pathway, increasing IL-8 transcription." (PMID 41446042, 2025).
tumor (5 papers, 2018 to 2025). "OAZ2 mRNA expression was strongly associated with several levels of tumor immune infiltration and correlated with ESTIMATEScore, ImmuneScore, and Stromal Score (all P < 0.05)." (PMID 40032914, 2025). "Additionally, OAZ2’s association with immune features such as tumor mutational burden (TMB), microsatellite instability (MSI), and immune infiltration underscores its integral role in the tumor microenvironment." (PMID 40032914, 2025). "Our findings support the potential of OAZ2 as a valuable biomarker and suggest its role as a therapeutic target, especially for modulating immune responses in the tumor microenvironment." (PMID 40032914, 2025). "We observed that OAZ2 expression is significantly lower in tumor tissues compared to adjacent normal tissues and is closely linked with overall survival (OS)." (PMID 40032914, 2025). "OAZ2 expression was found to be lower in tumor tissues compared to normal tissues (P < 0.05)." (PMID 40032914, 2025). "In contrast to tumors, the adjacent non-tumor tissues harbored eight genes with recurrent HBV integration, including FN1, DCC, OAZ2, ANO3, ENOX1, GRIK4, NPAT, and SNCAIP." (PMID 34209079, 2021). "These comprehensive findings position OAZ2 as a promising biomarker for COAD prognosis and a potential target for therapeutic intervention, with evidence supporting its regulatory effects on cell dynamics and tumor aggressiveness." (PMID 40032914, 2025). "Analyzing the whole-blood expression signature of four growth factor-related genes (ARAF, BRAF, KRAS, and RAF-1) and four genes involved in metabolism (ATP6V1H, OAZ2, PANK2, and PLD3), combined with tumor grade, they were able to predict the efficacy of PRRT with an accuracy of 95%." (PMID 33809226, 2021). "Additionally, the increased expression of AZIN2, the antagonist of OAZ2, in COAD tissues suggests a competitive interplay that could influence polyamine biosynthesis and tumor dynamics." (PMID 40032914, 2025). "Laboratory experiments further revealed that the protein and mRNA levels of OAZ2 are significantly diminished in COAD compared to adjacent normal tissues, while its antagonist AZIN2 shows elevated expression, suggesting a competitive interaction that may regulate tumor behavior." (PMID 40032914, 2025).
OAZ2 also shares sentences with these, for which no sentence is quoted: colorectal adenocarcinoma (1 paper); diabetes (1); neonatal diabetes mellitus (1); neuroblastoma (1); non-alcoholic fatty liver disease (1); type 2 diabetes (1).